CD40 (CD40 molecule)
Diseases named in the same sentence as CD40 in open-access papers (continued):
Sharing a sentence is not in itself a finding about the gene and the disease.
cancer (continued). "Among them, CD40 holds great promise for cancer immunotherapy." (PMID 39103878, 2024). "Immunotherapeutic interventions could represent an alternative approach to evaluate the CD40/CD40L axis, given the multifaceted effects of CD40 signaling, which position it as a potential target in cancer immunotherapy." (PMID 39625893, 2024). "Furthermore, engineered dendritic cells expressing CD40 bispecific antibodies showing anti-cancer activity through enhanced DC and T cell activity, hold promise as vaccines against several cancers." (PMID 37896948, 2023). "Moreover, Hyp PDT induced phagocytosis of cancer cells by DCs and induced upregulation of maturation markers CD80, CD86 and CD40 to a larger extent than DCs co-cultured with F/T treated cancer cells." (PMID 36839652, 2023). "Moreover, CD40 is also detected in different cancer cells, whereas its ligand, CD40L, is hardly found in normal or malignant epithelial cells." (PMID 37970926, 2023). "The expression of CD40 and CD40L has been previously reported to be prominent in pathologic processes known to be associated with chronic inflammation and angiogenesis, such as cancer and inflammatory bowel and vascular diseases." (PMID 37958563, 2023). "CD40 is an essential co-stimulatory protein involved in the pro-inflammatory immune activation of antigen-presenting cells like dendritic cells and immunosuppressive macrophages within the cancer landscape." (PMID 37799714, 2023). "Another randomized phase 2 trial conducted by researchers at the university of Pennsylvania and parker institute for cancer immunotherapy evaluated the efficacy of nivolumab (anti-PD-1) and/or sotigalimab (CD40 agonistic antibody) with AG in patients with first-line metastatic pancreatic cancer." (PMID 36691032, 2023). "The activation of APCs and reprogramming of the immune state in the TME with agonistic CD40 monoclonal antibodies represent a promising therapeutical strategy for the treatment of patients with cancer and the activation of APCs can further support T cell-based antitumor immunity." (PMID 36823405, 2023). "This implies that when CD40-activated B cells APCs are used as immunotherapy in cancer patients, they may perform an APC function and activate antigen specific T cells for cytotoxic functions." (PMID 36159874, 2022). "Consistently, agonistic CD40 antibodies were shown to increase T-cell mediated cancer death and, in combination with chemotherapy, may rescue ICI sensitivity." (PMID 35626033, 2022). "In addition, the anti-CD40 RNA vaccine (BNT113) developed by Pfizer/BioNTech is currently recruiting previous and recurrent HPV16+ patients against major HPV-associated cancers in its phase I clinical trial." (PMID 36558778, 2022). "However, human CD40 Abs displayed only modest antitumor activity in cancer patients, characterized by low efficacy and dose-limiting toxicity." (PMID 35911742, 2022). "By specifically inducing CD40 stimulation in the presence of FAP, this novel bispecific antibody was demonstrated to overcome the systemic toxicity associated with the CD40 agonist, thereby providing a promising approach for cancer immunotherapy." (PMID 36263225, 2022). "Here, the rationale and early immunobiology of CD40 as a master regulator of dendritic cell activation is reviewed, with further contextualization and appreciation for the role of CD40 stimulation not only in cancer vaccines but also in other contemporary immune-oncology approaches." (PMID 34282297, 2022). "In addition, we explored the immunological effects of FOSCAN-PDT-treated cancer cells by analyzing the expression of the co-stimulatory molecules CD40, CD86, and major histocompatibility complex (MHC)-II on the surface of DCs after 24 h of co-culture." (PMID 35681703, 2022).
cancer (continued). "However, in the context of cancer vaccination, these precursor populations are relatively rare, so developing agonists of CD40 that can serve as adjuvants for vaccines is a promising pathway to promote both CD4+ and CD8 T cell responses following vaccination." (PMID 34282297, 2022). "CD40 activation may represent a strategy to reverse T-cell exhaustion, enhancing the anti-cancer effects of the TIME." (PMID 35626033, 2022). "In addition, CD40 agonism can potentially prime immune responses to novel T-cell epitopes further facilitating cancer eradication." (PMID 33392713, 2021). "Targeting CD40 with agonist antibodies is a promising approach to cancer immunotherapy." (PMID 33392713, 2021). "The important role that CD40 signaling plays in anti-cancer immunity prompted us to explore genes that may be included as potential co-targets with a CD40 agonist-based therapy." (PMID 33804039, 2021). "Although now anti-CD40 agonistic Ab is not used clinically, combination therapy with OK-432 and anti-CD40 agonistic Ab may have potential in novel cancer immunotherapy." (PMID 34209347, 2021). "Further studies are warranted to extensively evaluate CD40 agonists in cancer patients." (PMID 33804039, 2021). "After identifying the anti-tumoral role of CD40/CD40LG in pan-cancer analysis, we next explored whether any cancer type(s) may alter CD40 in tumorigenesis." (PMID 34758832, 2021). "Together, CD40 has emerged as a promising target for cancer immunotherapy." (PMID 34101617, 2021). "CD40 agonists have been used as adjuvants for cancer vaccine therapies." (PMID 33804039, 2021). "Tumor-targeted bispecific molecules like ABBV-428, a mesothelin-CD40 bispecific are also developed and may provide cancer-targeted activation of macrophages." (PMID 33919517, 2021). "Several CD40 agonist antibodies are currently evaluated in clinical trials for treatment of cancer." (PMID 33948686, 2021). "They contribute to cancer inhibition primarily via the CD8 T cell-mediated CTL response by activation of CD40 in an NO-dependent manner, suggesting that introducing a new agent favoring Tip-DC development may a be feasible option for cancer immunotherapy." (PMID 33499256, 2021). "CD40 represents an emerging immune-modulating target in cancer treatment." (PMID 32582531, 2020). "Therefore, the cancer cell membrane-bound CD40L for the local stimulation of a cancer-specific CD40 signaling is necessary to improve safety." (PMID 32370135, 2020). "Cluster of differentiation 40 (CD40) has gained much interest as an immunostimulatory molecule in a variety of solid cancers, but the broad expression of CD40 in multiple cell types limited its cancer-specific application." (PMID 32370135, 2020). "MOF-gated MS most efficiently enhances cancer antigen presentation, upregulates the expression of costimulatory molecules (CD40 and CD80), and promotes chemokine receptor CCR7 expression, which implies their great potential in cancer vaccines, compared with MS or MOF." (PMID 32737343, 2020). "Lastly, the clinical evidence confirmed that CD40 induced HPV16-specific Tscm cells need to be enhanced in cancer patients to prevent further progression of the disease or to induce even cure, and may be adopted as a potent immunotherapy." (PMID 32536922, 2020). "It appears that CD40 expression and its stimulation in cancer cells could be dependent on the cancer cell type-specific signaling pathway and the immune niche within the cancer microenvironment." (PMID 32256143, 2020). "Since soluble CD40 expression would suppress CD40LG+ T cells and contribute to immune escape mechanisms, it is critical to explore this splice variant in cancer cells." (PMID 32256143, 2020). "We have previously generated a mutant form of CD40L that is resistant to proteolytic cleavage, with retained expression at the cell membrane and we have shown that this mCD40L can induce apoptosis in CD40-expressing carcinomas, indicating its potential as an anti-cancer therapy." (PMID 31941968, 2020).
cancer (continued). "The use of CD40 agonists has also been tested as cancer immunotherapy in clinical settings." (PMID 33101304, 2020). "In carcinomas, the nature of CD40 ligand shapes the outcome of CD40 ligation." (PMID 31941968, 2020). "In addition, it has been found that, in patients with primary liver cancer (HCC), Bregs directly interact with cancer cells through CD40/CD154 signaling pathway and promote the growth and infiltration of HCC cells." (PMID 31662750, 2019). "This is predicted to have particularly strong synergy in CD40 expressing cancers." (PMID 30788290, 2019). "Another concern is that the blockage of the CD40-CD154 interaction may lead to unwanted effects in cancer patients given that treatment with CD40 agonists is beneficial for cancer patients." (PMID 31426619, 2019). "These dying cancer cells are efficiently phagocytosed by BMDCs, inducing their maturation and activation in a manner that depends on the ratio of the two cell types, as evidenced by increased surface expression of CD40 and CD86." (PMID 31842994, 2019). "MAPKKs such as MKK4/MKK7 can trigger death-inducing JNK activation and JNK/AP-1 induction underpins mCD40L-mediated death in UCC cells; however, p38 activation has never been directly implicated in CD40-mediated carcinoma cell death." (PMID 31815003, 2019). "Furthermore, cytoplasmic and membrane CD40 expression of carcinoma cells was positively correlated with each other (p = 0.017)." (PMID 31137630, 2019). "Activating DCs through CD40 also represents a promising anti-cancer immunotherapeutic approach." (PMID 29652910, 2018). "Our resultsabout the effects of sCD40L on cancer cells of pre-BALL patients were concomitant with the studies of Kedarand co-workers who showed CD40 ligation may deliversignals that induce apoptosis and growth arrest in B-cellmalignancies." (PMID 29308628, 2018). "Moreover, signaling mediated by CD40 stimulation can induce cell death in cancer cells, making this pathway an attractive target for cancer immunotherapy." (PMID 29129918, 2017). "In this regard, agonistic CD40 antibodies appear as a promising strategy for cancer immunotherapy." (PMID 29129918, 2017). "The presented data allow better understanding of the mechanism by which mCD40L induces cell death which could be exploited in the clinical development of CD40-targeted anti-cancer therapies." (PMID 26986513, 2016). "Furthermore, the utilization of IL15 in combination therapy with other cytokines (e.g. IL-21 or GMCSF), or co-stimulatory molecules (CD40) is a potential avenue to be explored to improve current cancer immunotherapy." (PMID 26822794, 2016). "Thus, the CD40-positive carcinoma EJ and Panc1 cell lines were transfected with NORE1A small interfering RNA (siRNA) and then infected with AdnL." (PMID 26986513, 2016). "Agonistic CD40 antibodies have been demonstrated to activate antigen-presenting cells (APCs) and enhance antitumour T cell responses, thereby providing a new therapeutic option in cancer immunotherapy." (PMID 25651850, 2015). "In addition, we also found that the presence of HDAC7 led to the upregulation of genes related to immune processes (IL16, FCGR2A, IRAK2, CD86 and CD40, among others) and cancer (RASSF4, RAB31, NEDD9 and RASSF2, among others)." (PMID 25675295, 2015). "CD40 mutant can also be considered as a possible target for anti-cancer immunotherapy." (PMID 24885116, 2014). "CD40LG, which is the ligand of CD40, has shown great potentials in cancer therapy." (PMID 25108500, 2014). "The ligand induces the apoptosis of CD40-positive cancer cells." (PMID 25117071, 2014). "Furthermore, anti-CD40 mAbs hold great promise for use as part of vaccines against cancers and infectious diseases [e.g., Ref." (PMID 25324844, 2014). "For example, an agonistic anti-CD40 antibody may serve as an ideal therapy to supplement standard cancer treatments such as chemotherapy." (PMID 24664420, 2014).
cancer (continued). "Therefore, the major therapeutic purpose was target activation of CD40, which leads to the intensified CD-dependent T cell activation and the resulting effective anti-cancer immune response." (PMID 25117071, 2014). "Some authors believe that the CD40L/CD40 pathway may inhibit cancer progression through only one mechanism, i.e., enhanced immune response or apoptosis induction." (PMID 25117071, 2014). "Study using locally administered anti-CD40 Ab in cancer patients that might avoid toxicity and generate an even better response seems warranted." (PMID 24955376, 2014). "The presence of CD40 molecule was first identified on cancer cells of urinary bladder." (PMID 25117071, 2014). "Also, in acute lymphoblastic leukemia, the activation of CD40 present on cancer cells by CD40L enhances the secretion of MDC and TARC; i.e., the proteins that play a role of chemoattractans for CCR4+ T cells." (PMID 25117071, 2014). "However, binding of CD40L fusion proteins to target antigens on the cancer cell surface promotes oligomerization and augmented activation of CD40 on neighboring immature DC." (PMID 24741998, 2014). "Targeted delivery of CD40L to cancer cells is a promising strategy that may help to trigger cancer-localized activation of CD40 and can be modified to exert additional anti-cancer activity via the targeting domain." (PMID 24741998, 2014). "In addition, a fully human CD40 agonist antibody, CP-870,893, has been tested in humans with advanced cancers, resulting in objective responses in 14% of patients." (PMID 24339824, 2013). "Although little known about the relation between microvilli and CD40, but these studies suggest that MF may enhance DC-T cell interaction to eliminate cancer cell." (PMID 24278103, 2013). "CD40 signaling is also gaining further interest in transplantation and cancer therapies." (PMID 22685601, 2012). "Thus, our data implicate TNIK in LMP1- and CD40-induced cancer and indicate the potential of TNIK as a future target for therapy of EBV and CD40-associated malignancies." (PMID 22904686, 2012). "CD40-activated B cells can be prepared at relatively low costs as a highly pure homogenous population that can be expanded from small amount of peripheral blood even from cancer patients." (PMID 22592077, 2012). "Binding of recombinant soluble CD40L or with a CD40 reactive monoclonal antibody may produce a direct inhibitory effect on cancer cells." (PMID 23125850, 2012). "Accumulating evidence suggests that CD40 contributes to the pathogenesis of cancer." (PMID 21912605, 2011). "Because CD40 is upregulated in many cancers it is a potential target for anti-cancer therapy." (PMID 21103345, 2010). "CD40 antibody or ligand is also being investigated in cancer therapy and vaccination." (PMID 20205811, 2010). "CD40 is also expressed in lymphoid malignancies and a number of carcinomas." (PMID 20211016, 2010). "We next examined the effect of E1AD24ncCD40L on the viability of CD40-positive carcinomas." (PMID 20211016, 2010). "Hence, we next examined CD40 expression on the TAg+ cancer cells." (PMID 40397730, 2025). "Given that only CD8+ T cells are capable of recognizing antigens presented on major histocompatibility complex class I (MHC-I), which are present on all somatic cells, CD40L expression by CD8+ T cells could potentiate anticancer immune responses against CD40-expressing cancer cells." (PMID 40397730, 2025). "In addition, previous studies have confirmed that: CD40 activation may represent a strategy to reverse T-cell exhaustion, enhancing the anti-cancer effects of the TIME." (PMID 38956290, 2024). "Therefore, depletion of B cells and reprogramming macrophages via CD40 agonist antibody may have potential use in cancer treatment." (PMID 36845095, 2023). "Indeed, CD40-stimulated B cells have been explored as a cellular vaccine in several cancer models." (PMID 34282297, 2022).
cancer (continued). "Additionally, CD40 agonism could provide important co-stimulation to enhance the efficacy of anti-cancer vaccines." (PMID 36077755, 2022). "Thus, there are multiple aspects of CD40 stimulation that naturally align with the goals of cancer vaccines, and when our lab prepares CD40-stimulated DCs for cellular vaccines in murine models, we perform quality control by assessing their expression of IL-12 and CD70." (PMID 34282297, 2022). "However, upon CD40 costimulation, macrophages secrete NO, IL-12, and IFNγ, which are characteristic for proinflammatory M1-like activation state that leads to apoptotic-destruction of cancer cells in vitro and in vivo independent on T cell activity." (PMID 33919517, 2021). "We have previously shown that cancer development can trigger an accumulation of myeloid cells and extracellular matrix deposition in the liver, which may explain this differential role for myeloid cells in mediating CD40-induced liver toxicity." (PMID 34101617, 2021). "In our study, we also showed that many genes participate in the different pathways in cancer such as TRAF3, which encode a member of the TNF receptor-associated factor (TRAF) protein family and can associate with TNF receptor (TNFR) superfamily which participates in the signal transduction of CD40." (PMID 31775867, 2019). "However, the mechanism and function of CD40-mediated inflammatory DCs in cancer immunity are unknown." (PMID 25651850, 2015). "This is an important cytokine that plays a role in cancer, with two protein families implicated in the signaling mediated by the TNF receptor: 1) death-domain proteins, such as TRADD, FADD, TNFR1, RIP; and 2) TRAF domain-containing proteins, such as TNFR2, CD40, TRAF1, TRAF6." (PMID 26143641, 2015). "To determine the combined effect of CD40 activation and GM-CSF production on the maturation and the stability of the DC phenotype over time, we transduced CML-DC with untargeted or CD40-targeted Ad-GM-CSF or Ad encoding the carcinoma-embryonic antigen as a control vector (Ad-CEA)." (PMID 14520439, 2003). "Given their significant impact in immune regulation, CD40 and CD40L have become important targets in antibody-based cancer and autoimmune disorder therapies." (PMID 40683864, 2025). "There were also significant interactions between insulin-expressing cancer cells and immune cells, namely CD40LG (INS+FOSlow, INS+) − CD40 (B cell) and APP (INS+) − TREM2 + TYROBP (macrophage)." (PMID 40438247, 2025). "Immune-modulating proteins such as CXCR4, CD40, IL7R, TGFBR1, and SEMA4D are frequently targeted for cancer intervention studies." (PMID 40805206, 2025). "Conversely, our findings regarding the protective effects of CD40 and CCL4 (OR = 0.857, p = 0.015; OR = 0.896, p = 0.049) highlight the complexity of immune‐inflammatory interactions in cancer." (PMID 40682474, 2025). "After demonstrating that CD40L+CD8+ T cells target CD40+TAg+ cancer cells directly, inducing cell death through a CD40L-CD40 interaction, we sought to extend our investigation to another in vivo cancer cell model." (PMID 40397730, 2025). "We also included markers to detect regulations of checkpoint molecules on cancer cells and monocytes (PDL1, CD40) as well as checkpoint and activation markers on T and NK cells (CD107a, CD137, PD1, NKG2D, NKG2A, CD62L)." (PMID 39791733, 2024). "The interaction between CD40 and CD40L enhances immune and inflammatory responses against cancer cells." (PMID 39120299, 2024). "TNFRSF members and their cognate ligands play a major role in lymphoid tissue development and homeostasis and numerous members, including CD137, CD40, and OX40, are key targets for cancer immunotherapy." (PMID 39033322, 2024). "Canonical NF-kappa B signalling inhibition has been proposed for cancer therapy and further research should analyse TNF-alpha and CD40 roles as SLNs predictive markers." (PMID 39199652, 2024).